CTTN (cortactin)
Description:
Contributes to the organization of the actin cytoskeleton and cell shape. Plays a role in the formation of lamellipodia and in cell migration. Plays a role in the regulation of neuron morphology, axon growth and formation of neuronal growth cones (By similarity). Through its interaction with CTTNBP2, involved in the regulation of neuronal spine density (By similarity). Plays a role in focal adhesion assembly and turnover (By similarity). In complex with ABL1 and MYLK regulates cortical actin-based cytoskeletal rearrangement critical to sphingosine 1-phosphate (S1P)-mediated endothelial cell (EC) barrier enhancement. Plays a role in intracellular protein transport and endocytosis, and in modulating the levels of potassium channels present at the cell membrane. Plays a role in receptor-mediated endocytosis via clathrin-coated pits (By similarity). Required for stabilization of KCNH1 channels at the cell membrane. Plays a role in the invasiveness of cancer cells, and the formation of metastases.
Synonyms: EMS1
Tractability: Antibody: UniProt places it where antibodies can reach, with high confidence; its Gene Ontology location is reachable by antibodies, with high confidence; the Human Protein Atlas places it where antibodies can reach. PROTAC: UniProt records ubiquitination sites on it; ubiquitination databases record sites on it; its protein half-life has been measured.
Gene: Protein-coding gene on chromosome 11 (70,398,404 to 70,436,584, forward strand). Ensembl gene ENSG00000085733.
Subcellular location: Cytoplasm, cytoskeleton; Cell projection, lamellipodium; Cell projection, ruffle; Cell projection, dendrite; Cell projection; Cell membrane; Cell projection, podosome; Cell junction; Cell junction, focal adhesion; Membrane, clathrin-coated pit; Cell projection, dendritic spine; Cytoplasm, cell cortex; Endoplasmic reticulum
Subcellular location (Human Protein Atlas): Plasma membrane; Vesicles; Golgi apparatus
Pathways (Reactome):
Signal Transduction: RHO GTPases activate PAKs
Vesicle-mediated transport: Clathrin-mediated endocytosis
Gene Ontology:
Molecular function: cadherin binding; profilin binding; protein binding; Arp2/3 complex binding; proline-rich region binding
Biological process: intracellular protein transport; positive regulation of actin filament polymerization; positive regulation of smooth muscle contraction; actin cytoskeleton organization; cell motility; focal adhesion assembly; lamellipodium organization; neuron projection morphogenesis; receptor-mediated endocytosis; regulation of axon extension; signal transduction; modification of postsynaptic actin cytoskeleton; modification of postsynaptic structure; positive regulation of chemotaxis; regulation of cell projection assembly; regulation of mitophagy
Cellular component: actin filament; cell cortex; cortical cytoskeleton; cytoplasm; focal adhesion; lamellipodium; plasma membrane; voltage-gated potassium channel complex; clathrin-coated pit; cytoskeleton; cytosol; endocytic vesicle; endoplasmic reticulum; growth cone; ruffle; anchoring junction; cell junction; dendrite; dendritic spine; glutamatergic synapse; mitotic spindle midzone; podosome; postsynapse; postsynaptic actin cytoskeleton
Genetic constraint (gnomAD): Loss-of-function variants: 27 observed, 77.59 expected, observed/expected ratio (o/e) 0.35, 90% interval 0.25 to 0.48. The upper end of that interval is the gene's LOEUF score, 0.48, which puts it in group 2 of 6, group 1 being the genes least tolerant of losing a copy. Missense variants: 631 observed, 736.37 expected, observed/expected ratio (o/e) 0.86, 90% interval 0.8 to 0.92. Synonymous variants: 298 observed, 297.45 expected, observed/expected ratio (o/e) 1, 90% interval 0.91 to 1.1.
Homologues: Orthologues: macaque CTTN (98% identical), mouse Cttn (92% identical), guinea pig CTTN (91% identical), chimpanzee CTTN (91% identical), pig CTTN (91% identical), rabbit CTTN (86% identical), rat Cttn (85% identical), dog CTTN (85% identical), tropical clawed frog cttn (69% identical), zebrafish cttn (64% identical). Paralogues in human: HCLS1 (41% identical), DBNL (18% identical), DBN1 (14% identical), COTL1 (6% identical).
Diseases named in the same sentence as CTTN in open-access papers:
CTTN is named in the same sentence as 137 diseases in open-access papers, as found by Europe PMC text mining. Sharing a sentence is not in itself a finding about the gene and the disease. The quoted sentences say what the papers report.
breast carcinoma (84 papers, 2006 to 2025). "CTTN overexpression was associated with overexpression of gene sets related to stem cells, breast cancer relapse, EMT, and the b-catenin/TCF complex, and these effects were validated by quantitative real-time polymerase chain reaction (qRT-PCR)." (PMID 36831511, 2023). "Cortactin and fascin have been implicated in endosomal trafficking to invadopodia in breast cancer cells, resulting in the release of sEVs that were enriched with invadopodial proteins such as MT1-MMP." (PMID 37014551, 2023). "This assumption is supported by a recent study where cortactin overexpression in a HER2-type breast cancer was found to be associated with poor clinical outcome like other carcinomas." (PMID 37761244, 2023). "Here we report that ROR1 associates with cortactin in primary breast-cancer cells or in MCF7 transfected to express ROR1." (PMID 31667337, 2019). "Elevated cortactin expression has been linked to tumorigenesis, and has been shown to correlate with poor clinical outcome in breast cancer, head and neck squamous cell carcinoma, hepatocellular carcinoma, colorectal adenocarcinoma, and melanoma." (PMID 30976201, 2019). "In the present study, we found that Wnt5a induces ROR1 to associate with cortactin, which undergoes tyrosine phosphorylation in breast-cancer PDX cells or MCF7 cells transfected to express ROR1." (PMID 31667337, 2019). "For example, gene amplification studies have shown that the gene EMS1 (from human) encodes cortactin, which was overexpressed in a variety of tumors, such as breast cancers as well as head and neck tumors." (PMID 29152154, 2017). "This expression correlates with that of two other cytoskeletal proteins thought to be linked to breast cancer invasiveness, cortactin and fascin." (PMID 27009365, 2016). "Previously, amplification of the gene that encodes CTTN has been reported in approximately 15% of primary metastatic breast carcinomas and approximately 30% of head and neck squamous cell carcinomas." (PMID 27603901, 2016). "In breast cancer cells, cortactin is associated with the invadopodium, and overexpression of cortactin leads to increased cellular motility and invasiveness." (PMID 24808960, 2014). "The findings indicated CTTN expression associated with larger tumor size of BrCa could describe cortactin as an effective variable and call to question its role in advanced histologic grade of breast carcinoma for future studies." (PMID 33407452, 2021). "Interestingly, mammalian PKD1 is associated with the F-actin binding proteins cortactin and paxillin in invasive breast cancer cells where it may regulate cell adhesion and motility." (PMID 17592635, 2007). "As another mechanism, Wnt5a induces ROR1 to recruit cortactin to promote breast cancer cell migration and metastasis." (PMID 39905197, 2025). "About 20% of HER2+ breast cancers had abnormal CTTN copy numbers and/or expression, and the frequencies for CCND1 were similar, while alterations in the other genes were found at relatively low frequencies." (PMID 36831511, 2023). "Treatment with the Wnt signaling inhibitor was able to overcome CTTN-induced trastuzumab resistance in HER2+ breast cancer." (PMID 36831511, 2023). "In agreement with this, we report that CTTN induces CSC-like properties via Wnt signaling in breast cancer, suggesting that CTTN is involved in tumor initiation as well as progression." (PMID 36831511, 2023). "BPGAP1 colocalizes in lamellipodia with cortactin, which is known to regulate Arp2/3 complex–stimulated actin branching in lamellipodia, including in breast cancer MCF7 cells." (PMID 36598812, 2023). "Taken together, these data suggest that amplification and overexpression of CTTN are biomarkers for a poor prognosis in HER2+ breast cancer." (PMID 36831511, 2023). "CTTN Overexpression resulted in insensitivity to trastuzumab in trastuzumab-sensitive HER2+ breast cancer cell lines." (PMID 36831511, 2023).
breast carcinoma (continued). "In this study we explored the potential role of CTTN in inducing trastuzumab resistance of HER2+ breast cancers." (PMID 36831511, 2023). "We compared cortactin expression and clinicopathological factors according to the molecular subtypes of breast cancer." (PMID 37761244, 2023). "To the best of our knowledge, we are the first to propose a role of CTTN in the trastuzumab resistance of HER+ breast cancer." (PMID 36831511, 2023). "In breast cancer, in vivo and in vitro experimental data have been used to investigate the effects of CTTN expression on tumor development, growth, and metastasis." (PMID 37761244, 2023). "Amplification of cortactin is found in 15% of primary breast cancers and 29% of head and neck squamous cell carcinomas." (PMID 37761244, 2023). "We established lentiviral-induced CTTN overexpression and shRNA-mediated CTTN knockdown in various breast cancer cells to clarify the functional significance of CTTN in HER2+ breast cancer." (PMID 36831511, 2023). "CTTN expression was significantly higher in ER+/HER2+ breast cancer (right), and high expression levels were significantly correlated with amplification of CTTN (r = 0.75, p < 0.001) and HER2 expression (r = 0.2, p < 0.001)." (PMID 36831511, 2023). "Although studies on the correlation between cortactin expression and prognosis in breast cancer have been published, any correlation between cortactin expression and prognosis according to the molecular subtype has not been evaluated." (PMID 37761244, 2023). "Histone deacetylase 6 (HDAC6) is reported to deacetylase cell microtubule structures, such as α-Tubulin and cortactin, and increase the formation of invadopodia that promotes breast cancer cell migration and invasion." (PMID 35216622, 2022). "Our study uncovered a novel pathway that regulates cortactin expression and invadopodia formation in breast cancer metastasis." (PMID 36137995, 2022). "For example, in breast cancer patients, increased binding of cofilin to cortactin has been evident in promoting the formation of protrusions in aggressive breast cancers." (PMID 34678587, 2022). "It was demonstrated that EGFR-Src-Arg-cortactin pathway mediates functional maturation of invadopodia and breast cancer cell invasion, and the overexpression of the EGF receptor enhanced intravasation." (PMID 35158871, 2022). "Overexpression of cortactin/CTTN is linked to metastatic disease in head and neck cancer, breast cancer, oesophageal cancer, hepatocellular carcinoma, melanoma and colorectal cancer." (PMID 32709847, 2020). "Recent work has further demonstrated that in breast cancer cells protein-tyrosine phosphatase 1B (PTP1B) regulates the phosphorylation status at Y-421 of cortactin during invadopodium precursor assembly." (PMID 31936446, 2020). "Another study showed that the interaction of the surface protein ROR1 expressed in breast cancer cells interacts with cortactin and plays an important role in breast cancer cell migration and metastasis." (PMID 32210163, 2020). "We noted that the ARHGEF1 i.p. generated from lysates of breast-cancer PDX treated with cortactin siRNA had less capacity to generate activated RhoA than the ARHGEF1 i.p. of PDX treated with control, nonspecific siRNA." (PMID 31667337, 2019). "Vav2 is a guanine nucleotide exchange factor that activates Rho family GTPases and binds via its SH2 domain to phosphorylated cortactin to support ECM degradation by invasive MDA-MB-231 breast cancer cells." (PMID 31514269, 2019). "Culture of breast-cancer PDX cells in serum-free media resulted in the samples having lower levels of Y421-phosphorylated cortactin over time." (PMID 31667337, 2019). "In conclusion, the present study demonstrates a previously unrecognized ROR1/cortactin/ARHGEF1-dependent pathway leading to activation of RhoA in response to Wnt5a in breast-cancer cells." (PMID 31667337, 2019).
breast carcinoma (continued). "Pyk2 colocalizes with cortactin to invadopodia of breast cancer cells and regulates EGF–induced cortactin phosphorylation through Src‐mediated Abl‐related gene (Arg) activation, leading to actin polymerization and breast cancer cell invasion." (PMID 31368612, 2019). "The ROR1–PRD was essential for ROR1 to complex with cortactin and increase breast-cancer-cell migration in response to Wnt5a." (PMID 31667337, 2019). "Signaling activated by epidermal growth factor (EGF) triggers the cortactin-mediated maturation of invadopodia that are required for invasion by different aggressive tumor cells, including breast cancer cells." (PMID 31514269, 2019). "Immunoblot analysis of anti-cortactin or anti-ARHGEF1 i.p. by using lysates made from ROR1+ breast-cancer PDX cells revealed that ARHGEF1 associated with cortactin, and more specifically Y421-phosphorylated cortactin." (PMID 31667337, 2019). "Src is overexpressed in several solid cancers including breast, colon, and ovarian cancer, and is essential for breast cancer invadopodia formation via downstream regulators such as cortactin and Tsk5." (PMID 30909510, 2019). "Immunoblotting of whole protein cell lysates of eight PDAC cell lines and the breast carcinoma cell line MCF-7 as a positive control showed cortactin expression in all tested cell lines." (PMID 30976201, 2019). "Immunoblot analyses of anti-ROR1 or anti-cortactin immune precipitates confirmed that cortactin complexed with ROR1 in breast-cancer PDX cells." (PMID 31667337, 2019). "Cortactin is localised in breast cancer cell invadopodia, where it regulates actin stabilisation and the recruitment of ECM proteases to the invasive interface." (PMID 30909510, 2019). "Collectively, these studies demonstrate that the interaction of ROR1 with cortactin plays an important role in breast-cancer-cell migration and metastasis." (PMID 31667337, 2019). "Mass spectrometry (MS) analyses of anti-ROR1 mAb immune precipitates (i.p.)from lysates of ROR1-expressing breast-cancer PDX revealed cortactin in addition to ROR1." (PMID 31667337, 2019). "The apparent involvement of Arg and cortactin in distant metastasis across all hormone receptor statuses suggests that they have a synergistic general role in promoting breast cancer metastasis." (PMID 29774130, 2018). "Careful proteogenomic analysis of breast cancer patient databases revealed a correlation between increased Arg and cortactin expression to metastatic dissemination and poor patient prognosis." (PMID 29774130, 2018). "To assess the involvement of ABL kinases and cortactin in metastatic dissemination in breast cancer patients, we integrated DNA, RNA, and protein expression data of breast cancer tumors from TCGA and compared them for hormone- and HER2-receptor status." (PMID 29774130, 2018). "Together, these observations suggest that overexpression of ABL2 and CTTN, either individually or synergistically, is correlated with breast cancer metastasis and poor patient prognosis." (PMID 29774130, 2018). "To assess the involvement of ABL kinases and cortactin in metastatic dissemination and the clinical potential of their inhibition, we analyzed microarray expression levels of 1,650 breast cancer samples." (PMID 29774130, 2018). "This hierarchy was contradictory with previous studies describing the direct interaction of Syk and cortactin in breast cancer cells, and the impact of Src on Syk phosphorylation in colon cancer cells, opposite to our observations." (PMID 28306714, 2017). "Conversely, inhibition of Src did not affect the Syk catalytic activity, but both are required to induce cortactin phosphorylation in breast cancer cells." (PMID 28306714, 2017). "Using both rat MTLn3 and human MDA-MB-231 breast carcinoma cell lines stably expressing eGFP-Mena, eGFP-MenaINV and eGFP-Mena11a, we found that all of these Mena isoforms co-localize with cortactin and Tks5 at invadopodium precursors." (PMID 27824079, 2016).